MLKL (mixed lineage kinase domain like pseudokinase)
Diseases named in the same sentence as MLKL in open-access papers (continued):
Sharing a sentence is not in itself a finding about the gene and the disease.
tumor (continued). "Taken together, these data demonstrate that tumor cells undergoing RIPK3/MLKL-mediated necroptotic cell death can induce uptake of tumor debris by and maturation of bystander APCs." (PMID 40345706, 2025). "Reduced cross-presentation associated with MLKL−/− tumors resulted in impaired cross-priming and ICI-mediated expansion of tumor antigen-specific cytotoxic T cells." (PMID 40345706, 2025). "Western blot analysis further confirmed that N-GSDMD/E, c-CASP3/7, and p-MLKL were significantly upregulated in various GBM tumor cells following stimulation with cinobufagin." (PMID 39901195, 2025). "Smart, biocompatible nanoparticles can be engineered to precisely deliver extracellular-acting PFPs (e.g., PRF-1 and granulysin) directly to tumor sites or to regulate the expression and activation of intracellular PFPs (e.g., GSDMs and MLKL)." (PMID 40691738, 2025). "MLKL-mRNA therapy induces tumor neoantigen-specific T cell responses, which are dependent on type I IFN signaling and Batf3+ DCs." (PMID 41235238, 2025). "The dependency on tumor cell-intrinsic activity of the necroptosis executioner MLKL for ICI immunotherapy was found across different mouse strains and tumor models." (PMID 40345706, 2025). "Immunohistochemical staining of RIP1/MLKL/RIP3 of nude mouse subcutaneous tumor model shows the same result." (PMID 39619148, 2024). "MLKL mRNA expression in tumor tissues was significantly higher in TNBC patients than in those with non-TNBC subtypes." (PMID 38474369, 2024). "An important example is the finding that glucose deprivation instead of RIPK1 led to activation of MLKL and necroptosis by the release of mitochondrial DNA into the cytoplasm of tumor cells in an experimental model of breast cancer." (PMID 39062119, 2024). "p-MLKL in CT26 KO tumor tissue was mainly locked in the nucleus, while N-GSDMD and N-GSDME mainly existed in the cytoplasm and cell membrane." (PMID 38740747, 2024). "In keratinocyte-derived tumours, such as head and neck SCC, a substantial amount of necroptosis has been reported and high levels of phosphorylated MLKL were shown to correlate with lymph node metastasis and tumour progression." (PMID 38649745, 2024). "Interference with MLKL decreases capping actin protein (CAPG) content, confirming that MLKL/CAPG-induced necroptosis significantly reduces tumor volume in mice." (PMID 38164173, 2024). "The necroptotic signaling pathway mediated by RIPK1, RIPK3, and MLKL regulates the function of TAMs, influencing tumor progression." (PMID 39575419, 2024). "MLKL, a key executor of necroptosis, regulates tumor development, progression, and metastasis through both RIPK3-dependent and independent mechanisms, including receptor internalization, extracellular vesicle formation, and inflammation regulation." (PMID 39439891, 2024). "Kaplan–Meier survival analysis showed that extensive necroptosis (p-MLKL high) or high tumor-cell RAGE expression correlated with shorter overall survival rate (OS) and progression-free survival rate (PFS)." (PMID 38926796, 2024). "To further verify the regulatory relationship between TRAF6 and the RIPK1-RIPK3-MLKL signaling axis, we performed a subcutaneous transplantation tumor model of high TRAF6 expressing cells through RIPK3−/− and MLKL−/− mice of C57BL/6 genetic background." (PMID 36604411, 2023). "Necroptotic molecules, such as RIPK3 and MLKL, were already reported as prognostic markers in many tumor types." (PMID 37651429, 2023). "We analyzed the association between the CNVs of necroptosis key genes, RIPK3 and MLKL, and the level of immune infiltration of various immune cells using the Tumor Immune Estimation Resource (TIMER) database." (PMID 37000317, 2023). "Treating melanoma cells with miRNA coding for the necroptosis mediator MLKL can also induce necroptosis and elicit a potent anti-tumor response with increased infiltration of immune cells." (PMID 37373523, 2023).
tumor (continued). "MLKL-deficiency in HCC cells increases the cell susceptibility to metabolic stress-induced parthanatos in the liver microenvironment and enhances anti-tumor immune surveillance." (PMID 36650126, 2023). "Western blot analysis also showed that the protein expression levels of p-RIPK3 and p-MLKL in the tumor site were significantly upregulated after treatment with different doses of EBI in mice." (PMID 37397499, 2023). "We found that blocking tumor necroptosis by MLKL deletion led to the dramatic reduction of tumor metastasis and significantly elevated anti-tumor activity of tumor-infiltrating and peripheral blood T cells." (PMID 36703228, 2023). "Our results above reveal an impact of MLKL on HCC tumor growth that requires its interaction with the local microenvironment in the liver." (PMID 36650126, 2023). "We then performed subcutaneous MOCK(TRAF6), MOCK(WT), MOCK(RIPK3−/−) and MOCK (MLKL−/−) group of cell transplantation tumor models through RIPK3−/− and MLKL−/− mice of C57BL/6 genetic background." (PMID 36604411, 2023). "We also observed that high expression of MLKL had a significant inhibitory effect on tumor growth and increased neutrophil infiltration in vivo." (PMID 37000317, 2023). "Another study showed that ZBP1 expression was significantly increased in mouse colon adenocarcinoma MC38 cells and mouse melanoma B16-SIY cells after radiation treatment, which subsequently activated MLKL to induce tumor cell necroptosis." (PMID 37771585, 2023). "Subsequently, we examined the relationship between the two core necroptosis-related genes, RIPK3 and MLKL, and tumor immune infiltration across different types of cancer." (PMID 37000317, 2023). "The subcutaneous tumor tissues with MLKL overexpression displayed a large number of neutrophil infiltrations, while the subcutaneous tumor tissues with knockout MLKL had virtually no neutrophil infiltration." (PMID 37000317, 2023). "We herein discover that MLKL suppresses anti-tumor immune response in HCC while MLKL depletion enhances the efficacy of anti-PD-1 therapy in the syngeneic HCC models." (PMID 36650126, 2023). "The combination of a PD-1 inhibitor with MLKL mRNA was proved effective in suppressing tumor growth in vivo." (PMID 37373523, 2023). "Our findings indicate that the 12 necroptosis genes, particularly MLKL, play a crucial role in tumor immune cell infiltration and tumor cell stemness." (PMID 37000317, 2023). "Mechanistically, shikonin increases ROS production and upregulates the expression levels of RIPK1, RIPK3, and MLKL, which prompts necroptosis in apoptosis-resistant tumor cells." (PMID 36482419, 2022). "In mice, inducing spontaneous necroptosis in subcutaneous murine tumors by overexpressing MLKL mRNA synergized efficiently with anti-PD1 immunotherapy to elicit potent anti-tumor immunity." (PMID 36059470, 2022). "For example, the pro-necrosis proteins, such as RIPK1, RIPK3, and MLKL, play key roles in promoting tumor growth." (PMID 36353119, 2022). "Necroptosis is a form of programmed cell death regulated by three major mediators, RIPK1, RIPK3, and MLKL, is a key process in cancer biology, including tumor initiation and progression, invasion and migration, and tumor immunosuppression." (PMID 35965497, 2022). "Some studies have found that NRGs have a role in a variety of tumor-related activities, however they appear to be a double-edged sword.MLKL,RIPK1 and RIPK3 are the key mediators among them." (PMID 36601479, 2022). "In a follow-up study, they employed wild-type VACV for targeted intratumoral delivery of MLKL, which led to the activation of necroptosis-like tumor cell death in vitro." (PMID 36755812, 2022). "To unveil the function of MLKL in intestinal tumorigenesis, we analyzed tumor progression in Apcmin/+Mlkl-/-mice and Apcmin/+ mice." (PMID 33767595, 2021). "Pre-NAC MLKL status was also significantly correlated with pN (p = 0.042) and tumor differentiation (p = 0.010)." (PMID 34503283, 2021).
tumor (continued). "It was shown that intratumoral delivery of MLKL mRNA stimulates anti-tumor immunity against neo-epitopes, a process that was dependent on CD8α+ DCs, which are proficient in antigen cross-presentation." (PMID 33658037, 2021). "In vitro transfection of B16 (melanoma) and CT26 (colon carcinoma) tumor cells with MLKL or tBID was achieved using LipofectamineTM as a transfection agent, while in vivo delivery of the mRNA was achieved through electroporation." (PMID 33658037, 2021). "LAMP2 and HSP90α were also highly expressed in the tumor internal hypoxia area compared to the normoxia tumor area in vivo; however, the expression of MLKL was decreased in hypoxia." (PMID 33440739, 2021). "Next to this approach, Van Hoecke and colleagues evaluated intratumoral injection of hypo-inflammatory mRNA encoding the key execution protein in the necroptosis pathway, MLKL, immediately followed by electroporation of the tumor." (PMID 33658037, 2021). "We therefore also compared the correlation of necroptosis activation (pMLKL) and MLKL with tumor-infiltrating inflammatory/immune cells." (PMID 34083572, 2021). "We also detected the p-MLKL levels of other tumor cells at 48 hours after irradiation, but the results showed that none of the HepG2 and Hep2 cells following carbon ion and X-ray treatment underwent necroptosis." (PMID 33531997, 2021). "What’s more, phosphorylation- RIP3 and MLKL activation induced by P. aeruginosa infection resulted in tumor cell necrotic cell death and HMGB1 production, indicating that P. aeruginosa can cause immunogenic cell death." (PMID 33643911, 2020). "Western blotting of six pairs of patients’ tumor-TAE tissues also shows a higher level of MLKL in tumor tissues, whesrea the RIP1 and RIP3 levels vary between different patients." (PMID 32444644, 2020). "Particularly, the main executor of necroptosis, MLKL, was highly expressed at the invasion front of the tumor." (PMID 31999765, 2020). "In this point, we propose that patients who have a relatively low level of MLKL in tumor tissues are more likely to respond to TRAIL receptor agonists due to the perturbation in endosomal trafficking of the TRAIL receptor agonist." (PMID 32917855, 2020). "Pervious works identified that expression of RIP1/3 and MLKL was not only necessary to the necroptosis pathway but also contributes to the immunogenic cell death in TC-1 tumor cells." (PMID 33643911, 2020). "We detected the active, phosphorylated form of RIP3 and MLKL in the lysate cell supernatants of bacteria treated tumor cells, indicating that bacteria were able to induce necrotic cell death activation." (PMID 33643911, 2020). "First, we defined that P. aeruginosa directly trigger tumor cell death in a necrotic-like death by increasing the activate form of phosphorylation- RIP3 and MLKL expression in tumor cells." (PMID 33643911, 2020). "Kaplan–Meier survival analyses shows that high level of all these three markers correlate with shorter overall survival (OS), whereas high level of p-MLKL and tumor necrosis also correlate with shorter progression-free survival (PFS)." (PMID 32444644, 2020). "Intra-tumor therapy with an MLKL-mRNA-based vaccine inhibit CAC growth reshaped the tumor microenvironment inducing systemic antitumor response directed against neo-epitopes." (PMID 33643911, 2020). "We first analyzed the level of p-MLKL, MLKL, and tumor necrosis in HNSCC patient tissues as well as their correlation with clinicopathological features." (PMID 32444644, 2020). "To unveil the necroptotic status in HNSCC, we first assessed the expression of phospho-MLKL, which is currently the most recognized marker for necroptosis, in tumor and tumor-adjacent epithelial tissues (TAE) of HNSCC patients." (PMID 32444644, 2020). "In contradiction to our results, multiple previous research had demonstrated that MLKL is significantly downregulated in tumor tissues and low-level MLKL can be correlated with poor prognosis." (PMID 32444644, 2020).
tumor (continued). "Early study highlighted the beneficial effects of RIPK3 and MLKL inhibitors on inflammation in animal models of disease ranging from ischemic injury to autoimmune disorders and neoplasia." (PMID 32854254, 2020). "Since MLKL (mixed lineage kinase domain-like pseudokinase) is the executioner and the most exclusive biomarker for necroptosis 30, we tested its active form, phosphorylated MLKL (p-MLKL) in xenograft nude mice tumor tissues via immunostaining." (PMID 32863941, 2020). "We included 191 HNSCC patients who received radical dissections between 2013 and 2018 and analyzed the expression of MLKL, p-MLKL in their tumor, and TAE tissues using immunohistochemistry." (PMID 32444644, 2020). "We measured relative mRNA expression levels of RIPK1, RIPK3, and MLKL in tumor and corresponding normal lung tissues." (PMID 32742497, 2020). "The blockage of necroptosis regulation genes RIP1/RIP3/MLKL, especially MLKL, by small chemical inhibitors or genetic depletion markedly attenuated tumor repopulation in in vitro and in vivo and even attenuated tumorigenicity in mice." (PMID 31706322, 2019). "In conclusion, results from this study demonstrated that radiation-induced necroptosis depends on the activation of RIP1/RIP3/MLKL pathway, and the necroptosis contributes to tumor repopulation through the MLKL/JNK/IL-8 axis." (PMID 31706322, 2019). "In the orthotopic MVT-1 breast cancer model, we found that blocking necroptosis of tumor cells by MLKL deletion significantly inhibited lung metastasis." (PMID 31922095, 2019). "We provided evidence that radiation-induced necroptosis is dependent on sequential activation of RIP1/RIP3/MLKL, and necroptosis contributes to tumor repopulation through the MLKL/JNK/IL-8 axis." (PMID 31706322, 2019). "Taking together our findings provide a new insight into the function of MLKL molecule and the mechanism of tumor repopulation." (PMID 31706322, 2019). "As shown in our publication, we found that MLKL phosphorylation happens in dying cells in tumor necrotic areas and demonstrated that necroptosis is indeed engaged during tumor necrosis." (PMID 31922095, 2019). "More importantly, tumor necrosis is largely suppressed upon necroptosis blockage by the deletion of MLKL gene and interestingly, the remaining tumor death in MLKL-null tumors is apoptotic." (PMID 31922095, 2019). "Vaccination with necroptotic cancer cells facilitates efficient anti-tumor immunity, and administration of mRNA coding for MLKL induces anti-tumor immunity." (PMID 31665027, 2019). "In conclusion, we show that by using VNB photoporation it is feasible to deliver, in vitro, caspase-3/-8 or MLKL protein to murine B16 tumor cells." (PMID 31480289, 2019). "Mechanistically, we found that Batf3-dependent DCs and type I IFN signaling were vital to raise tumor-specific T cell responses upon MLKL-mRNA treatment." (PMID 30143632, 2018). "We have developed a potentially generic treatment method to induce tumor antigen-specific cellular immunity based on the transient intra-tumor expression of the necroptosis-inducing factor MLKL." (PMID 31225452, 2018). "To take the MLKL-mRNA approach a step closer from bench to bedside, we demonstrated that the new anti-tumor mRNA therapy can also elicit protective anti-tumor responses against a human lymphoma in mice with a reconstituted human adaptive immune system." (PMID 31225452, 2018). "Since tBid- and MLKL-mRNA treatment induced very similar levels of tumor cell death, we can also conclude that the mere induction of cell death is not sufficient to induce a strong antitumor response." (PMID 30143632, 2018). "In the mouse tumor model, we found that the combination of MLKL-mRNA treatment and systemic administration of a PD-1 inhibiting antibody has a superior antitumor effect compared with either treatment alone." (PMID 31225452, 2018).
tumor (continued). "On day 6, the tumor that was inoculated first was treated with MLKL mRNA in combination with i.p. administration of anti-PD1 or an isotype control antibody." (PMID 30143632, 2018). "Compared to mock treated mice, a strong influx of cDC1 and cDC2 DCs was apparent in the tumor bed and its draining lymph nodes in mice that had been treated intratumorally with mRNA coding for MLKL." (PMID 30143632, 2018). "Strikingly, MLKL-mRNA treatment of the tumors elicited strong T cell responses directed against tumor neo-epitopes." (PMID 30143632, 2018). "Receptor-interacting protein kinase 3 and MLKL act as tumor suppressors, and thus are valuable therapeutic tools, since many cancers develop necroptosis resistance [reviewed in Ref." (PMID 29527209, 2018). "Ex vivo analysis of the tumor tissue revealed that after MLKL mRNA-treatment, a considerable fraction of the tumor cells had lost their membrane integrity." (PMID 31225452, 2018). "Formulations of MLKL mRNA that can successfully target tumor tissue after injection, are conceivable future developments." (PMID 31225452, 2018). "The anti-PD1 combination therapy was significantly more effective at suppressing the growth of the primary treated tumor and of the distant untreated tumor than the MLKL-mRNA treatment combined with the control antibody." (PMID 30143632, 2018). "We systematically searched PubMed, Embase, Web of Science and CNKI to obtain all relevant articles about the prognostic value of abnormally expressed MLKL in patients with any type of tumor." (PMID 30005626, 2018). "We have shown that the MLKL-mRNA treatment can elicit in situ immunogenic cell death that results in robust tumor neo-antigen-specific immune responses." (PMID 31225452, 2018). "In a repeat experiment in this human tumor model, MLKL mRNA outperformed tBid mRNA treatment in controlling tumor growth." (PMID 30143632, 2018). "Here, the authors show that the intra-tumor delivery of mRNA that codes for the necroptosis effector MLKL triggers neo-epitope-specific anti-tumor T cell responses and inhibits primary tumor growth and lung metastasis." (PMID 30143632, 2018). "In our study, we evaluated the effects of the necroptotic genes RIPK1, RIPK3, and MLKL in tumor growth and tumor resistance to therapy." (PMID 26959742, 2016). "Here we show that, contrary to expectation, necroptotic factors RIPK1, RIPK3, and MLKL promote tumor growth." (PMID 26959742, 2016). "Our results indicate that tumor samples from both cohorts exhibit low and high levels of staining for phosphorylated MLKL." (PMID 26959742, 2016). "Mice bearing MLKL-deficient or RIPK3-deficient tumors failed to control tumor growth in response to anti-PD-1/anti-CTLA-4 immunotherapy." (PMID 40345706, 2025). "At tumor site, MUC1@ACS NPs released SK and Chi-Ag NPs in response to acidic environment, causing tumor cell necrosis by increasing expression levels of tetrameric MLKL, RIPK3, p-RIPK3, and, which subsequently triggered ICD." (PMID 40689201, 2025). "Overall, these studies highlighted that inducing necroptosis through the delivery of MLKL mRNA or protein can enhance anti-tumor immunity, emphasizing its potential as a treatment to trigger immunogenic tumor cell death and consequent activation of anti-tumor immune reaction." (PMID 40691738, 2025). "Trigger MLKL-mediated cell death;Enhance inflammatory signals to stimulate anti-tumor immunity." (PMID 40264780, 2025). "However, it is paradoxical about the role of MLKL in autophagy regulation in tumor cells, such as mouse Neuro-2a and L929 cells, and human HEK293 and HT29 cells." (PMID 40070567, 2025). "We did not observe significantly more aggressive tumor growth and associated reduced host survival in animals bearing MLKL−/− tumors in the absence of ICI treatment." (PMID 40345706, 2025).